PDPN (podoplanin)
Diseases named in the same sentence as PDPN in open-access papers (continued):
Sharing a sentence is not in itself a finding about the gene and the disease.
cancer (continued). "Podoplanin is a critical promoter of tumorigenesis, migration, invasion, EMT, cancer-associated thrombosis, and chemoresistance." (PMID 35163233, 2022). "Immunofluorescence using the antibody Lp2 demonstrated that cancer-type PDPN was positive on the cell surface of LN319, GIC0222, and TGS01 cells." (PMID 35991754, 2022). "In this study, we established a third generation of Lp2 scFv-based CAR that reacts with cancer-type PDPN in GBM." (PMID 35991754, 2022). "Among the commonly used CAF markers, only the expression of the PDPN gene increased during the cultivation of normal fibroblasts with cancer cells." (PMID 36263012, 2022). "In oral squamous cell carcinoma, mtHSP70 is secreted by cancer cells in an autocrine manner; subsequently, extracellular mtHSP70 binds to PDPN, which plays a role in cell adhesion, participating in regulating the growth and invasiveness of cancer cells." (PMID 35180892, 2022). "Experimental observations have proved that podoplanin expression increases cancer cell motility, thereby enhancing local invasion, as reflected by the advanced pathological T stage of human SCC with high levels of podoplanin expression." (PMID 36247509, 2022). "Cancer-cells can also express molecules such as podoplanin and thrombin, which interact with platelet CLEC-2 and PAR1/2 receptors to activate and aggregate platelets." (PMID 35159000, 2022). "A recent study also shows that PDPN regulates the migration of MSCs, as these cells upregulate PDPN at sites of infection, chronic inflammation, and cancer." (PMID 35743928, 2022). "In the same way, Podoplanin expression was also upregulated in samples of malignant tumors such as SCC compared with healthy skin." (PMID 35956111, 2022). "Preclinical studies have identified PDPN as a therapeutic target to combat several cancers including oral cancer and nasopharyngeal cancer." (PMID 33420101, 2021). "The LpMab-2 antibody recognized this specific site and effectively inhibits PDPN-CLEC-2 interaction only in the cancer microenvironment." (PMID 34322381, 2021). "Cumulative evidence supports that platelets can directly interact with PDPN-expressing cancer cells via C-type lectin-like receptor 2 (CLEC2), contributing to cancer cell invasion and metastasis." (PMID 34987523, 2021). "The proliferation index of PC-9 cells in hybrid cancer organoids, containing podoplanin-overexpressing CAFs, was significantly higher than that of PC-9 cells in organoids containing control CAFs." (PMID 33445709, 2021). "Altogether, these results suggest that selective blockade of CLEC-2 function on the platelet surface or disruption of PDPN-CLEC-2 interaction would be effective for anti-cancer therapy." (PMID 34322381, 2021). "Podoplanin is a 44-kDa glycoprotein that was initially characterised as a platelet-aggregation factor on cancer cells from colorectal tumours." (PMID 33580106, 2021). "These PDPN mAbs specifically inhibited PDPN-mediated platelet aggregation and cancer metastasis in the murine experimental models." (PMID 34987523, 2021). "Several preclinical studies have demonstrated that anti-PDPN antibodies inhibit cancer metastasis and cancer progression." (PMID 34685483, 2021). "According to the Cancer Genome Atlas analysis, head and neck cancer patients present much higher PDPN expression levels compared to other types of cancer patients." (PMID 34987523, 2021). "Its counter piece is podoplanin, also known as aggrus, which appears in several tissues and is overexpressed on certain types of cancer cells." (PMID 33937274, 2021). "We and others have previously reported that cancer cell overexpression of podoplanin promotes cancer cell invasiveness." (PMID 32599908, 2020). "Dual immunohistochemical staining further confirmed the spatial locations of DDR1 and PDPN in OSCC tissues indicative of collective cancer cell invasion." (PMID 32244515, 2020).
cancer (continued). "The upregulation of podoplanin expression has been reported in both human cancers and in experimentally generated animal tumors." (PMID 32599908, 2020). "In contrast, the siRNA-mediated downregulation of PDPN in high-PDPN-expressing cancer cells conversely resulted in a mesenchymal-to-epithelial transition in some marker genes, decreasing cell motility and invasive capacity." (PMID 32581653, 2020). "Cancer cell expressed podoplanin has been reported to promote both single cell invasion and epithelial-mesenchymal transition (EMT), as well as collective cell invasion." (PMID 32599908, 2020). "In summary, here we present evidence of a physical interaction of podoplanin with CD44s and CD44v isoforms expressed in human SCC cells, suggesting a functional interplay between podoplanin and CD44 likely associated with cancer cell invasion." (PMID 33003440, 2020). "In this study, the efficacy and safety of the cancer-specific anti-canine PDPN chimeric antibody, P38Bf, was evaluated." (PMID 33238582, 2020). "This correlation has also been observed in other squamous cell carcinoma, as well as glioma, mesothelioma, and melanoma, establishing PDPN as a malignant tumor biomarker." (PMID 32581653, 2020). "Although it reacts with PDPN expressed by the cancer cells, it has been shown to be unreactive to PDPN expressed by the normal cells." (PMID 32858947, 2020). "To solve this issue, we have established a cancer-specific monoclonal antibody (CasMab) against human PDPN, which recognizes the cancer-specific aberrant glycosylation of human PDPN." (PMID 33238582, 2020). "For instance, in cutaneous squamous cell carcinoma (cSCC), PDPN is significantly upregulated in metastatic (p = 0.002) and poorly differentiated (p = 0.003) cancer patients." (PMID 32408907, 2020). "CasMab is an antibody that recognizes both the cancer-specific glycosylation and the PDPN-derived peptide sequence." (PMID 32858947, 2020). "Cancer cell overexpression of podoplanin has been reported to promote lymphangiogenesis in a number of human carcinomas and mouse models of carcinogenesis." (PMID 32599908, 2020). "According to those results, the value of PDPN expression as a marker for cancer stem cells in LUSC should be critically evaluated in future studies." (PMID 32408907, 2020). "Here, we review the application of T cell immunotherapy using specific antigen receptor molecules and discuss the possibility of the clinical application of podoplanin-targeted CAR derived from a cancer-specific monoclonal antibody (CasMab)." (PMID 32858947, 2020). "Many reports have suggested that cancer stemness is responsible for chemo- and radio-resistance, and in turn, PDPN has been shown to be related to cancer stemness in human SCC." (PMID 32380790, 2020). "A large number of metastasis researches have been carried out using various established cancer cells and have identified numerous novel metastasis-related genes, including AGGRUS/PDPN, CDC42, and VEGF." (PMID 32325684, 2020). "Cancer cell expression of podoplanin in SCCs of the oral cavity and the lung correlates with increased cancer invasiveness, lymph node metastasis and the shorter survival time of patients." (PMID 32599908, 2020). "The expression of podoplanin on cancer cells is one of the representative mechanisms of platelet activation by cancer cells." (PMID 33363175, 2020). "All of these studies also showed a strong correlation between cancer prognosis and podoplanin, especially its existence in cervical lymph nodes." (PMID 31212608, 2019). "In this study, we showed that SZ168 inhibited platelet aggregation induced by PDPN-expressing human cancer cells in a dose-dependent manner." (PMID 31208371, 2019). "In conclusion, we have established a pull-down and slot blot-based system for the efficient screening of compounds that inhibit the podoplanin-CLEC-2 interaction for use in the treatment of cancer and thrombosis." (PMID 31553741, 2019).
cancer (continued). "Podoplanin expression is upregulated in both epithelial and mesenchymal cell compartments during inflammation and cancer, and a growing body of evidence indicates that it plays an important role in these pathologies." (PMID 30736372, 2019). "Mesenchymal stromal cells (MSCs) upregulate podoplanin at sites of infection, chronic inflammation and cancer." (PMID 30745334, 2019). "Podoplanin expression is upregulated in different cell types, including fibroblasts, macrophages, T helper cells, and epithelial cells, during inflammation and cancer, where it plays important roles." (PMID 30736372, 2019). "In this review, we describe the diverse roles of podoplanin in inflammation and cancer, depict the protein ligands of podoplanin identified so far, and discuss the mechanistic basis for the involvement of podoplanin in all these processes." (PMID 30736372, 2019). "Podoplanin-induced platelet aggregation is involved in the correct separation of the lymphatic and blood vasculatures during development and in cancer metastasis." (PMID 30736372, 2019). "Flow cytometry assay showed that SZ163 and SZ168 also detected endogenous PDPN in the human cancer cell lines C8161 and CNE-2, similarly to the 18H5 as positive control antibody." (PMID 31208371, 2019). "Recently, it was established that SOX2 can also increase the expression of podoplanin in cancer stem cells." (PMID 31508790, 2019). "Studies on the PDPN function in cultured cancer cells, in mouse cancer models and in human cancer biopsies have indicated that PDPN promotes cells invasion in vitro and in vivo." (PMID 30654768, 2019). "Following these and other avenues will significantly improve our knowledge on the function of podoplanin in inflammation and cancer in the near future." (PMID 30736372, 2019). "In contrast, Suzuki and colleagues showed that podoplanin expression in a lung squamoid cancer cell line restrained lymph node metastasis and suppressed lymphangiogenesis, in association with downregulation of VEGF-C." (PMID 30736372, 2019). "It seems that podoplanin-positive CAFs generate “tracks” in the extracellular matrix and promote cancer cell growth and invasion independently of MMP activity." (PMID 30736372, 2019). "Podoplanin (PDPN) is involved in lymphangiogenesis and is seen as a marker of poor prognosis and a potential therapeutic target in several cancers." (PMID 31387228, 2019). "As a result, podoplanin plays an important role in a variety of physiological and pathological (e.g., inflammation, thrombus formation, and cancer progression) processes, as well as in cellular adhesion, migration, and chemotaxis." (PMID 31578434, 2019). "Podoplanin expression is upregulated in both epithelial and mesenchymal cells during ischemia-hypoxia, inflammation, and cancer." (PMID 31578434, 2019). "Podoplanin-mediated stimulation of collective cell migration agrees with the fact that, more often, podoplanin co-localizes with E-cadherin at the invasive front of human carcinomas." (PMID 30736372, 2019). "Activated CAFs, in turn, induce podoplanin expression in carcinoma cells through the TGF-β–Smad pathway and enhance cell invasion by activating EGFR, AKT, and ERK signaling." (PMID 30736372, 2019). "It has been suggested that cancer cells expel podoplanin into the bloodstream in order to have an effect on thrombosis at distant sites." (PMID 30314362, 2018). "Therefore, it may be thought that the PDPN conformation is different for different cancer cell types due to the diversity of sialic acid bindings, and the diversity affects the affinities of antibodies to PDPN, causing the opposing diagnosis for the cancer by PDPN immunostaining." (PMID 29765527, 2018). "PDPN overexpressed in cancer cells or fibroblasts of cancerous stroma significantly correlates with lymph node metastasis." (PMID 30018456, 2018). "A novel mAb LpMab-23 was recently established for human cancer-type PDPN using the cancer-specific mAb (CasMab) technology." (PMID 29765527, 2018).
cancer (continued). "Our findings strongly suggest that podoplanin is a promising therapeutic target for treating cancer." (PMID 30279963, 2018). "Recently, PDPN was found in several other cancers, such as brain tumors, squamous cell carcinomas, germ cell tumors, and mesotheliomas." (PMID 28702871, 2018). "This transmembrane glycoprotein also promotes cancer cell migration and invasion, since the podoplanin cytoplasmic tail interacts with ezrin and/or moesin, members of the ERM protein family, to activate RhoA and promote epithelial-mesenchymal transition (EMT)." (PMID 28938000, 2017). "A substantial amount of clinical data shows that the presence of PDPN-expressing CAFs correlates with poor patients’ prognosis in such cancers." (PMID 28938000, 2017). "The first eight of the nineteen targets, PIAS3, p27, RAB10, DBF4, DUSP14, RBPMS, PDPN and CLTC, were considered to be closely associated with cancer progression after a literature review." (PMID 28120918, 2017). "Podoplanin (PDPN), an O-glycosylated, transmembrane, mucin-type glycoprotein, is expressed by cancer associated fibroblasts (CAFs)." (PMID 28416768, 2017). "Podoplanin, a transmembrane glycoprotein, is up-regulated in a variety of human cancer cells, especially those derived from squamous stratified epithelia (SCCs)." (PMID 28912668, 2017). "Overall, the role of podoplanin expressed by CAFs in cancer progression remains ambiguous and inconsistent." (PMID 28938000, 2017). "Podoplanin, a powerful inducer of platelet aggregation, binds with its receptor, C-type lectin receptor, on the tumor surface to induce cancer growth and metastasis." (PMID 29163847, 2017). "It was proposed that enhanced RhoA activity facilitates PDPN-positive-fibroblasts to create a microenvironment promoting cancer growth." (PMID 28938000, 2017). "Podoplanin expression has been studied in a variety of cancer cells in relation to lymphatic vasculature." (PMID 28416768, 2017). "It must be pointed out that NKL3 cells, similar to MDA-MB-231 cancer cells, adhere less to PDPN expressing fibroblasts." (PMID 28416768, 2017). "Recent studies have shown that this interaction between podoplanin and C-type lectin receptor is a promising target for cancer therapy." (PMID 29163847, 2017). "This suggests that podoplanin is only a marker of a specific subpopulation of fibroblasts, which interacts with cancer cells." (PMID 28938000, 2017). "In this type of carcinoma, there is also a high possibility of the same malignant progression initiated by podoplanin." (PMID 28642617, 2017). "Our finding is expected to shed light on the clinical development of podoplanin-targeting cancer therapy." (PMID 26684030, 2016). "Although the biological function of PDPN is not fully understood, many studies have investigated the crucial role of PDPN expression in human cancers with the aim of employing PDPN expression as a prognostic marker." (PMID 27313335, 2016). "Podoplanin is frequently overexpressed in various malignant tumors such as squamous cell carcinoma, mesothelioma, glioblastoma, bladder tumors, and osteosarcoma." (PMID 26684030, 2016). "Cancer cells with high PDPN expression have higher malignant potential because of enhanced platelet aggregation, which promotes alteration of cell motility, metastasis and epithelial-mesenchymal transition." (PMID 25803614, 2015). "The chimeric anti-PDPN antibodies ChMS-1 and hP2–0 were developed to prevent cancer growth and metastases." (PMID 26528756, 2015). "Co-culture with CAFs-PDPN suppressed the viable NCI-H82 cancer cell number to 84.5% of the number of cancer cells after co-culturing with CAFs-Ctrl (P < 0.01)." (PMID 25909164, 2015). "These authors demonstrated that podoplanin was involved in cancer cell invasion and tumorigenesis through the use of experimental procedures, such as the Matrigel invasion assay and an in vivo mouse study." (PMID 26095281, 2015).
cancer (continued). "2CP has potential as an anti-metastatic agent in cancer and as a tool for elucidating the molecular mechanism of PDPN-induced CLEC-2 activation." (PMID 26528756, 2015). "Various approaches for preventing PDPN/CLEC-2 interactions have been developed for anti-cancer therapy." (PMID 26528756, 2015). "Anti-podoplanin MAbs with high sensitivity and specificity are necessary to analyze the physiological function of podoplanin in normal tissues and cancers." (PMID 25723283, 2015). "Co-culture with CAFs-PDPN decreased the viable NCI-H69 cell number to 79.5% of the number of cancer cells after co-culturing with CAFs-Ctrl (P < 0.01)." (PMID 25909164, 2015). "Taken together, the results show that LpMab-2 is expected to be useful for molecular targeting therapy against podoplanin-expressing cancers." (PMID 25080943, 2014). "We next examined the reactivity of the anti-podoplanin mAbs against several podoplanin-expressing cancer cell lines and normal cell lines using flow cytometry." (PMID 25080943, 2014). "Despite the specificity of its expression in lymphatic endothelium, PDPN has also been detected in various cancers." (PMID 24797369, 2014). "The novel mAbs reacted with podoplanin-expressing cancer cell lines, including LN31913, PC-1023, NCI-H22624, LN229/hPDPN, RERF-LC-AI/hPDPN, Y-MESO14/hPDPN16, and HSC3/hPDPN." (PMID 25080943, 2014). "Podoplanin (PDPN/Aggrus/T1α), a platelet aggregation-inducing mucin-like sialoglycoprotein, is highly expressed in many cancers and normal tissues." (PMID 25080943, 2014). "Immunostaining of LpMab-2 and LpMab-7 against podoplanin demonstrated predominantly cell-surface patterns in cancer cells." (PMID 25080943, 2014). "PDPN-expressing cancer cells have enhanced malignant potential due to enhancement of platelet aggregation, which promotes metastasis, alteration of cell morphology and motility, and epithelial-mesenchymal transition." (PMID 24354864, 2013). "In recent clinicopathological studies of other cancer types, PDPN expression in the cancerous stroma was reported to be a prognostic indicator, but the effects on prognosis varied depending on the cancer type." (PMID 24354864, 2013). "We also found that PDPN expression in CAFs was affected by both cancer cell-stromal interactions and environmental conditions." (PMID 24354864, 2013). "The presence of PDPN-expressing fibroblasts has been reported to be a prognostic indicator in several types of cancer, but outcomes vary according to the type of cancer." (PMID 24354864, 2013). "We investigated the effects of cancer cells on PDPN expression in CAFs using an indirect co-culture system." (PMID 24354864, 2013). "Understanding the molecular mechanisms of PDPN expression is important for the development of new therapeutic strategies for the treatment of malignant tumors with PDPN-positive fibroblasts." (PMID 24354864, 2013). "In cultured CAFs, PDPN positivity changed over time under several conditions including co-culture with cancer cells, different culture media, and addition of growth factor." (PMID 24354864, 2013). "PDPN is a type-I integral membrane glycoprotein, which expression was shown up-regulated in a number of different cancers." (PMID 24229053, 2013). "The majority of mechanistic data available on the cellular functions of PDPN come from studies of cancer progression and metastasis." (PMID 22988448, 2012). "This review will provide a comprehensive overview of the diverse roles of PDPN in development, immunology, and cancer." (PMID 22988448, 2012). "Expression of CFP-PDPN in these cells caused morphologic changes that were consistent with previous reports linking PDPN expression with increased invasiveness in cancer cells." (PMID 22884313, 2012). "Here, we describe how MASL can serve as a potent bioactive plant medicine that targets PDPN to combat cancer." (PMID 22844530, 2012).